S100B (S100 calcium binding protein B)
Diseases named in the same sentence as S100B in open-access papers (continued):
Sharing a sentence is not in itself a finding about the gene and the disease.
infection (46 papers, 2008 to 2026). The state of being infected such as from the introduction of a foreign agent such as serum, vaccine, antigenic substance or organism. "Despite the fact that validation studies are still currently underway in additional patient cohorts and the mechanisms underlying the increased susceptibility to infection cannot be definitely pinpointed, a genetically-determined hyperfunction of the S100B/RAGE axis is probably involved." (PMID 22114731, 2011). "Moreover, the influence of preceding infection/inflammation on hypoxic-ischemic brain injury is known to be critical in preterms, and prenatal inflammation is known to be associated with increased maternal and fetal S100B levels." (PMID 37292373, 2023). "The immunoreactivity of glial fibrillary acidic protein (GFAP) and S100β, markers of astrogliosis, were predominantly elevated in the hippocampal and internal capsule regions as the duration of infection increased." (PMID 40929057, 2025). "S100B is known as a protein produced by brain cells and is released into the bloodstream in conditions such as brain injury or infection." (PMID 38326816, 2024). "Toward this direction, the combined expression of the astrocytic markers GFAP and S100β was assessed through immunofluorescence experiments at 14 days post infection." (PMID 39468302, 2024). "One-fifth of upregulated DEPs in the AD retinas were related to immune responses, including HLA-DRB1, APOC1, S100A1, HLA-E, IBA1, and S100β, and involved lymphocyte and myelomonocyte activation in the presence of neuroinflammation and infection." (PMID 36773106, 2023). "On the other hand, S100B inhibition increased the colonic levels of IL-22 during infection (p = 0.008)." (PMID 34568098, 2021). "VEEV infection was limited to S100-β+ astrocytes and NeuN+ neurons in WT animals, whereas similar infection in Ifnar−/− animals led to GFP expression within BMECs and pericytes in both the cortex and cerebellum." (PMID 32047126, 2020). "When performing pairwise correlation for the ASD cases, BDNF had a significant positive correlation with the other neurodevelopmental factors, VEGF and S100b, and with the inflammatory/infection markers IgA and TARC." (PMID 31591381, 2019). "The infection of glial progenitor cells was confirmed by double staining with both S100β and ZIKV sera." (PMID 30083387, 2018). "S100B was sharply expressed in the late infection stage in mice with low-, medium- and high-dose infections; however a significant 4.80-fold increase was only evident in mice with low-dose infection at 20 wpi." (PMID 29273062, 2017). "We show in EcoHIV infected mice two-months post-infection, concentrations of S100B was significantly higher as compared to uninfected control mice; thus confirming our previous analysis of BBB permeability via sodium fluorescein assay." (PMID 26986758, 2016). "One reached peak level of serum S100B the day before developing ventriculitis, while peak levels for the other patient occurred on the same day as the infection was diagnosed." (PMID 23761779, 2013). "We found a dose-dependent increase in apoptosis with overexpression of intracellular APP or S100B through lentiviral infection or transient transfection into control HNPs." (PMID 21779383, 2011). "In contrast, S100B was promptly induced in infection, and declined thereafter to return to basal levels a week later, as revealed by gene and protein expression analysis in the lung and protein secretion in the bronchoalveolar lavage fluid (BAL)." (PMID 21423669, 2011). "We found that S100B neutralization decreased resistance to infection in WT mice as indicated by the increased fungal growth, PMN recruitment and inflammation in the lung, an effect that was mimicked by treatment with antibodies neutralizing RAGE engagement." (PMID 21423669, 2011). "Notably, both infection and S‐exposure also upregulated the expression of the neuronal stress marker S100B." (PMID 39950320, 2025).
infection (continued). "Moreover, we uncovered an enhanced expression of the S-100β glial marker 6, 8, and 10 weeks post infection, suggesting that the enteric glial cells were activated." (PMID 34094993, 2021). "While our study focused on the role of S100B activity during active infection, further studies on how manipulation of the intestinal S100B signaling could ameliorate CDI outcomes (such as recurrence and intestinal dysfunction) are needed." (PMID 34568098, 2021). "The expression level of S100B proteins increases in response to factors upregulated during infections such as TNFα, IL-1β, IL-6, and IL-8, also reported to be increased in prenatal infection models." (PMID 34741005, 2021). "Since remyelination depends upon the proliferation, migration, and differentiation of SC, S100β increase observed in our animal model, might reflect an attempt to revert the infection injury due to ML by increasing the presence of SC." (PMID 32696914, 2020). "Further analysis on purified lung cells from transgenic mice confirmed that epithelial cells were major sources of S100B in infection while Ager was expressed on epithelial cells, macrophages, dendritic cells (DCs) and polymorphonuclear neutrophils (PMNs), as described." (PMID 21423669, 2011). "The ability of S100B to bind nucleic acids, while qualifying S100B as possible sentinel for nucleic acid–mediated immune activation, also serves to explain the intracellular function of S100B in epithelial cells in infection." (PMID 21423669, 2011). "The transcriptional downregulation of s100b in infection led us to hypothesize that transcription factors downstream p38/TRIF would mediate this effect." (PMID 21423669, 2011). "We disclosed the complexity of signalling integration between different innate immune biosensors by showing that the spatiotemporal regulation of TLRs and RAGE by S100B limits pathogen– as well as danger–induced inflammation and ensures protection in infection." (PMID 21423669, 2011). "In terms of source of intracellular nucleic acids, consistent with the binding activity of S100B in vitro, we found that fungal RNA not only complexes with S100B in infection but also activates epithelial cells in a TLR3–dependent manner, as indicated by IRF3 phosphorylation." (PMID 21423669, 2011). "We resorted to lung epithelial cells as major sources of S100B in infection." (PMID 21423669, 2011). "However, S100B concentrations already peaked at 20 h after experimental infection and have a short serum half-life which may explain a high percentage of negative scores." (PMID 33028339, 2020). "Thus, the spatiotemporal regulation of TLRs and RAGE by S100B provides evidence for an evolving braking circuit in infection whereby an endogenous danger protects against pathogen–induced inflammation and a pathogen–sensing mechanism resolves danger–induced inflammation." (PMID 21423669, 2011). "In summary, the majority of CSF immune factors assayed remained unchanged throughout the course of infection, except for IL-12 (in two animals), TGF-1β and S100β." (PMID 41602558, 2026). "In our cohort, more severe strokes (represented by higher levels of S100B and higher NIHSS) were found in the infection group." (PMID 32209993, 2020). "The present study found that TGF-β1, TG2, S100B and GFAP were significantly elevated during early infection at 8 wpi, which was similar to results of our previous study." (PMID 29273062, 2017). "Because S100B production mainly occurred in infection via the TLR2/MyD88 pathway, our findings indicate the existence of an autocrine/paracrine loop by which TLR2–induced S100B binds to extracellular RAGE to inhibit TLR2 upon physical association." (PMID 21423669, 2011). "Furthermore, we found that approximately 88% of S100β-positive astrocytes in the Sc+PTSD and 85% in the shMAOB+PTSD groups were also mCherry positive, indicating high infection efficiency across astrocytes populations." (PMID 40717119, 2025).
infection (continued). "The results presented in the current study provide evidence that genetic variants in regulatory regions (cis-eQTLs) can up-regulate the C3, S100B, and SELENOS gene expression which might activate a prompt resolution of the infection." (PMID 33432064, 2021). "The involvement of the enteric nervous system, which is a source of S100B, in Clostridioides difficile (C. difficile) infection (CDI) is poorly understood although intestinal motility dysfunctions are known to occur following infection." (PMID 34568098, 2021). "Indeed, we have previously shown that microbial infection increased the levels of S100B that directly activated RAGE and targeting RAGE reduced infection and dampened inflammation." (PMID 34835243, 2021). "In a subanalysis, 16 patients with early infections were matched with 16 patients without infection according to S100B peak levels." (PMID 25613713, 2015). "In a subanalysis of patients matched for S100B levels, we showed that differences in inflammation markers in patients with and without infection were independent from the extent of brain lesion." (PMID 25613713, 2015). "Because TLR2 activates the inflammatory state of PMNs in infection and unrestrained inflammation occurred in condition of defective S100B/RAGE axis, we hypothesized that the S100B/RAGE axis may inhibit TLR2/MyD88–driven inflammation to the fungus." (PMID 21423669, 2011). "However, and in contrast to these authors, no induction of S100B was observed after 12 h co-cultivation, possibly due to different infection models." (PMID 27047454, 2016). "Of note, in 4 out of 20 patients with infection, no fitting matches could be identified according to S100B levels." (PMID 25613713, 2015). "As S100B did not correlate with antenatal inflammation in this study (to be noted, the latter is known to correlate with postnatal inflammation, it is possible that brain injury itself affects the immune response of the newborn, becoming more vulnerable to infections." (PMID 37292373, 2023). "Interestingly, CSF concentrations of t-tau and S100B were not affected by the infection." (PMID 31093802, 2019). "However, we can essentially rule out this possibility because following infection by GFAP-GFP AAVs, there were no GFP+ cells present in the GCL that co-localized with either Pax2, Sox9, GFAP, or S100β which are astrocyte markers." (PMID 34671605, 2021).
psychiatric disorder (41 papers, 2010 to 2025). A disorder characterized by behavioral and/or psychological abnormalities, often accompanied by physical symptoms. "In neurodegenerative, inflammatory, and psychiatric diseases, increased levels of S100B may be caused by secreted S100B or released from damaged astrocytes." (PMID 37759909, 2023). "S100B has been linked to glial pathology in several psychiatric disorders." (PMID 26941608, 2016). "High blood S100B levels have been linked to brain damage and psychiatric disorders." (PMID 25202915, 2014). "Numerous studies of different designs were published on circulating S100B levels in five major psychiatric disorders with a shared genetic background." (PMID 37759935, 2023). "Our literature search retrieved 111 original articles focused exclusively on circulating S100B in these five major psychiatric disorders." (PMID 37759935, 2023). "S100B is a calcium-binding protein widely studied in psychiatric disorders as a potential biomarker." (PMID 37759935, 2023). "Nevertheless, we excluded subjects with major psychiatric disorders, known to have a potential impact on S100B and BDNF." (PMID 35910248, 2022). "Serum levels of HSP70, HSP60, and S100B were assessed in a sample of participants with psychiatric disorders (n = 191) and a control group (CT) (n = 59) using enzyme-linked immunosorbent assay (ELISA)." (PMID 36527709, 2022). "S100B has been consistently shown to be involved in psychiatric diseases such as mood disorders and schizophrenia." (PMID 35910248, 2022). "Our results suggest that CSF APP, GDNF, and NCAM-1 levels are associated with psychiatric disorders, and that CSF HGF, S100B, and VEGF receptor 2 levels are related to psychiatric symptoms." (PMID 32439851, 2020). "In conclusion, our data suggest the involvement of state- (i.e., HGF, S100B, and VEGF receptor 2) and trait (i.e., APP, GDNF, and NCAM-1) markers associated with neuroplasticity in the pathology of psychiatric disorders." (PMID 32439851, 2020). "In psychiatric disorders, S100B was investigated by assessing serum levels, levels in cerebrospinal fluid (CSF) and variants in the S100B gene." (PMID 26364276, 2015). "Concordant with the increased inflammatory signal, there was a downregulation in mRNA expression of genes linked to neurodevelopment and myelination, neurotransmitter regulation, and psychiatric disorders including calcium binding Calb2 and S100b, as well as SNAP25, Pvalb, MAG, Olig1, and Olig2." (PMID 40059770, 2025). "S100B protein is a glial marker widely used in the investigation of brain damage and neurodegenerative and psychiatric diseases in patients and experimental models in which its extracellular levels are evaluated in cerebrospinal fluid (CSF), blood serum, or cell culture medium." (PMID 38068900, 2023). "S100B, a homodimeric Ca2+-binding protein, is produced and secreted by astrocytes, and its extracellular levels have been used as a glial marker in brain damage and neurodegenerative and psychiatric diseases; however, its mechanism of secretion is elusive." (PMID 38068900, 2023). "Our systematic review aimed to compare studies on peripheral S100B levels in five major psychiatric disorders with shared genetic backgrounds to reveal whether S100B alterations are disease-specific." (PMID 37759935, 2023). "Indeed, the decrease in serum S100B levels following treatment with antidepressants and antipsychotics suggests some clinical relevance of S100B to the pathophysiology of psychiatric disorders." (PMID 23547920, 2013). "The association of symptom severity with decreasing S100B levels is consistent with our prediction of inefficient glial function in ADHD rather than an overproduction resulting from apoptosis and brain damage reported for other major psychiatric disorders." (PMID 20534153, 2010).
psychiatric disorder (continued). "However, more studies are necessary for a comprehensive understanding of S100β on psychiatric disorders and if S100β is a promising biomarker peripherical of BBB disruption due to the adipocyte also secreting S100β-mediated cold stress contributing to sympathetic system activation." (PMID 39796167, 2025). "Finally, it cannot be determined whether the alteration of expression, processing or clearance of significant proteins (i.e., APP, GDNF, HGF, NCAM-1, S100B, and VEGF receptor 2) results in the association with psychiatric disorders." (PMID 32439851, 2020). "Alterations in peripheral S100B levels reported in psychiatric disorders seem to be non-disease- or trait-specific." (PMID 37759935, 2023). "However, as for the comparisons with healthy controls, this study showed that CSF S100B level was not altered in patients with psychiatric disorders, which is consistent with studies in 133 patients with BD26 and 31 with MDD24." (PMID 32439851, 2020). "However, while increased S100B levels in patients with SCZ have been interpreted as a marker of structural damage or, alternatively, as a sign of astroglial dysfunction, the role of GFAP (a classical marker of astrogliosis) in psychiatric disease remains controversial." (PMID 26733814, 2015).
brain diseases (20 papers, 2010 to 2024). "To choose the concentration of use of the compounds, we first exposed the astrocyte cultures to different concentrations of MG, FC, LPS or STZ and evaluated the level of GFAP and S100B, which are frequently associated with brain disorders." (PMID 38535311, 2024). "S100β, an 11 kDa soluble Ca2+-binding protein, is another astrogliosis marker that is released from astrocytes in inflammation-linked brain disorders, as well as by LPS, proinflammatory cytokines, and elevated [Ca2+]i." (PMID 35881483, 2022). "The dysfunction of these cells is widely associated with brain disorders, which are often characterized by variations in the astrocyte protein markers GFAP and S100B, in addition to alterations in some of its metabolic functions." (PMID 38535311, 2024). "Changes in plasma S100β concentration have been reported as an index of several brain diseases, including SZ." (PMID 37937262, 2023). "As an astrocytic marker, S100B can be easily detected in the serum, and an increase or decrease in levels has been observed in multiple known brain disorders." (PMID 31824318, 2019). "Reports show that RAGE-mediated inflammatory responses trigger S100B activated microglia stimulation in the brain, leading to neuronal damage and neurodegeneration and resulting in symptomatic brain disorders." (PMID 26733811, 2015). "S100B has been proposed as a marker of astroglial activation in brain disorders, and changes in its cerebrospinal fluid and/or serum content have been associated with various neurological and psychiatric diseases." (PMID 21970823, 2011). "The S100B traffic likely demands specific transporters, and it is possible that some brain diseases allow a higher S100B efflux." (PMID 20672003, 2010). "Our work might contribute to the understanding of the mechanism of secretion of S100B, a protein widely used as a marker of astroglial activation in experimental models and clinical studies of brain disorders." (PMID 38068900, 2023). "Together, these data contribute to our understanding of the effect of LPS on astrocytes, particularly on S100B secretion, and help us to interpret cerebrospinal fluid and serum changes of this protein in neuroinflammatory diseases and brain disorders in general." (PMID 21970823, 2011). "Over-expression of S100B has now been documented in a range of brain diseases." (PMID 21034449, 2010). "Despite the controversies on their brain specificity, S100B and NSE have been investigated in different brain diseases as peripheral markers of therapeutic interventions, as well as of neurological and neuropsychological outcome." (PMID 20105309, 2010). "Reports show that S100B triggers RAGE-mediated inflammatory responses and microglia stimulation in the brain, leading to neuronal damage and neurodegeneration and resulting in symptomatic brain disorders." (PMID 27242430, 2016). "On a more cautionary note, these results equally suggest that S100B can no longer be considered as a sole marker of astrocyte dysfunction in brain disease given its widespread distribution." (PMID 23705829, 2013).
cardiovascular diseases (9 papers, 2019 to 2024). "S100B protein has been implicated in many cardiovascular diseases." (PMID 37217870, 2023). "Not only is the S100B level increased in patients with cardiovascular disease but it is also increased in those with non-cardiovascular disease." (PMID 33796567, 2020). "Previous studies have shown that S100 protein family members are involved in cardiovascular disease, such as S100B, S100A8, S100A9, and S100A12." (PMID 31275446, 2019). "Newer ones such as galectin-3, lysophosphatidylcholine, copeptin, sST2, S100B, myeloperoxidase and GDF-15 have been extensively studied in recent years as alternatives with an increased sensitivity for cardiovascular diseases, but also with significant results in the field of neurology." (PMID 34821692, 2021).